ENSG00000289447 (novel transcript)
Gene: Long non-coding RNA gene on chromosome 6 (26,285,207 to 26,301,455, forward strand). Ensembl gene ENSG00000289447.
Gene Ontology:
Molecular function: triplet codon-amino acid adaptor activity
Biological process: translation